MPO (myeloperoxidase)
Diseases named in the same sentence as MPO in open-access papers (continued):
Sharing a sentence is not in itself a finding about the gene and the disease.
Chronic colitis (25 papers, 2012 to 2025). A chronic inflammatory disease of the large intestine (colon, cecum and rectum). "In inflammatory conditions like chronic colitis, myeloperoxidase (MPO) activity rises notably, producing superoxide radicals and other ROS that contribute to DNA damage and mutations, particularly in colon tumors." (PMID 39857404, 2025). "Combination treatments effectively mitigated colonic shortening, reduced neutrophil infiltration (measured via MPO activity) and normalised spleen weight in both acute and chronic colitis models." (PMID 40005963, 2025). "Like acute colitis, chronic colitis was associated with significant increases in plasma GLP-1 but no significant change in colonic levels, spleen-to body weight percentage, or spleen MPO activity, indicating extraintestinal involvement." (PMID 39682761, 2024). "In chronic colitis, sustained activation of neutrophils leads to the release of MPO, which contributes to tissue damage by generating ROS and other reactive intermediates." (PMID 37513865, 2023). "This work found that chronic colitis resulted in increased myeloperoxidase activity in the colon, as well as increased levels of proinflammatory cytokines IL-1β and CXCL1." (PMID 37512580, 2023). "The luminescence of DiL/DiD-BA/Res@NP is positively correlated with MPO level, which is a pro-inflammatory mediator commonly elevated in both acute and chronic colitis." (PMID 35236359, 2022). "Mice suffering from chronic colitis showed a significantly increased MPO and histological score in the colon samples." (PMID 30315190, 2018). "Furthermore, we found that mice induced with chronic colitis and fed −I3C diet had higher MPO activity than mice with DSS-induced with chronic colitis and fed +I3C diet." (PMID 38068838, 2023). "Our results revealed that the activities of MPO, NFκB DNA binding, and caspase-1, and the levels of active caspase-3 were significantly increased in the chronic colitis rat group compared with normal rats." (PMID 37513865, 2023). "Moreover, CR attenuated chronic colitis in mice in a dosing time-dependent manner based on measurements of disease activity index, colon length, malondialdehyde/myeloperoxidase activities and IL-1β/IL-6 levels." (PMID 34393786, 2021). "Results demonstrated that administration of PADF (10 mg/Kg/day) to mice with DSS chronic colitis significantly reversed the colon shortening, reduced the histological damage, neutrophil infiltration (as showed by MPO activity assay), and the production of inflammatory cytokines (IL-1β and TNF-α)." (PMID 32033338, 2020). "Furthermore, our investigation revealed a negative correlation between the levels of β-hydroxybutyrate in rats with chronic colitis and several inflammatory markers, including MPO activity, ROS production, NLRP3 levels, caspase-1 activity, NFκB DNA binding activity, and the NGSDMD." (PMID 37513865, 2023). "This system released over 70% of 5-ASA within 6–16 h at pH 7.0 and demonstrated therapeutic efficacy in a chronic colitis mouse model by significantly reducing the expression of IL-1β and TNF-α, as well as inflammatory markers such as MPO, H2O2, and MDA." (PMID 41219776, 2025). "We used the microbiota-derived MPO inhibitor, IPA, to examine differences in MPO inhibition as a comparator to genetic deletion of MPO on the development of acute and chronic colitis." (PMID 39133648, 2024). "The colonic samples obtained from mice with acute colitis were characterized by higher macrophage infiltration and MPO activity, whereas infiltration of CD4 + lymphocytes was substantially lower than in reactivated, chronic colitis." (PMID 37086302, 2024). "It decreased pro-inflammatory cytokines (myeloperoxidase (MPO), nitric oxide (NO), and TNF-α secretion) in the colon during acute and chronic colitis." (PMID 38202328, 2023). "The effect of CR on chronic colitis was accessed based on DAI, colon length, MDA/MPO activities and IL-1β/IL-6 levels as well as histopathological analysis." (PMID 34393786, 2021).
Chronic colitis (continued). "Given that MPO has nonenzymatic functions, we sought to determine the impact of enzymatic inhibition of MPO on acute and chronic colitis." (PMID 39133648, 2024). "Likewise, oral administration of genistein decreased TNBS-stimulated chronic colitis by inhibition of COX-2 mRNA and protein expression together with the colonic myeloperoxidase (MPO) activity in rat that applies useful anti-inflammatory effects in the treatment of IBD." (PMID 26379683, 2015).
colorectal cancer (25 papers, 2013 to 2025). A primary or metastatic malignant neoplasm that affects the colon or rectum. "High tumour infiltration by MPO‐expressing cells in breast and colorectal cancers has been associated with a significant improvement in prognosis." (PMID 38923838, 2024). "In colorectal cancer, açaí decreased myeloperoxidase (MPO) and cytokines such as tumor necrosis factor alpha (TNF-α), interleukin 1 beta (IL-1β) and interleukin 6 (IL-6), and inhibited cyclooxygenase 2 (COX-2), also reinforcing its anti-inflammatory effect." (PMID 40343252, 2025). "In colorectal cancer (CRC), the frequency of CD66+high neutrophils was positively associated with CRC malignancy, whereas myeloperoxidase (MPO+) neutrophils showed the opposite trend as a good prognostic factor." (PMID 40282474, 2025). "On the other hand, in vivo, T4 increases the expression of some inflammatory factors such as MPO, IL-1, COX2 and INOS that are associated with the development of colorectal cancer." (PMID 39165688, 2024). "In terms of macrophage and neutrophil phenotypes, previous studies indicated that MPO positive neutrophil infiltration predicts better survival and response to 5-FU-based chemotherapy in colorectal cancer." (PMID 35953652, 2023). "Though limited direct evidence that supports TAN and TAM interaction through MPO and the MMR is available, high density MPO-positive neutrophil infiltration has been reported in colorectal cancer." (PMID 35784290, 2022). "It has been observed that colorectal cancer infiltration with CD16+ high myeloperoxidase positive myeloid cells correlates with favorable outcome." (PMID 29983866, 2018). "Finally, based on a median low verses high gene expression split, high CSF3, MPO, and OLR1 gene expression was associated with reduced disease-specific survival (CSF3 and MPO) and overall survival (ORL1) in colorectal cancer." (PMID 36911097, 2023). "In addition, mice with colorectal cancer induction had a significant increase in the colonic level of MPO." (PMID 34684488, 2021). "However, higher tumor infiltration of myeloperoxidase (MPO)-positive neutrophils had a favorable prognosis in advanced gastric carcinoma, esophageal squamous cell carcinoma and colorectal cancer." (PMID 34572138, 2021). "The upregulation of immune-related genes such as MPO and DEFA3 highlights their potential as biomarkers for the detection of advanced colorectal cancer stages." (PMID 40003985, 2025). "The inclusion of immune-related transcripts, such as MPO and FCGR1A, in the early and advanced stages of colorectal cancer highlights the value of liquid biopsy for cancer detection." (PMID 40003985, 2025). "Clinical validation of MPO and FCGR1A underscores their potential as biomarkers for early adenoma detection and advanced colorectal cancer monitoring." (PMID 40003985, 2025). "Key transcripts, such as MPO, FCGR1A, DEFA4, and CD177, have been highlighted as potential biomarkers of colorectal cancer, underscoring the role of immune dysregulation in tumor development and progression." (PMID 40003985, 2025). "In colorectal cancer, another chemokine receptor, formyl peptide receptor (FPR1), is highly expressed in tumor-infiltrating, myeloperoxidase-positive (MPO+) cells." (PMID 33841132, 2020). "Among the top 10 deregulated genes, MMP2 (Matrix Metallopeptidase 2) is well known for its role in colorectal cancer invasion and EPSTI1 (Epithelial stromal interaction 1) and MPO (Myeloperoxidase) are related to tumor development." (PMID 30987352, 2019). "Moreover, MPO+ cells were more abundant in MSI (microsatellite instable) versus MSS (microsatellite stable) colorectal carcinomas, questioning MSI’s influence on host immune responses to CRC." (PMID 40149674, 2025). "Notably, IFI27 was linked to the symptomatic non-disease control group, DEFA4 to the non-advanced adenoma group, MPO to the advanced adenoma group, and CD177 to the colorectal cancer group." (PMID 40003985, 2025).
colorectal cancer (continued). "The identification of circulating biomarkers such as MPO and FCGR1A could contribute to the development of non-invasive screening tools for early colorectal cancer detection, offering potential clinical benefits through more personalized approaches to colorectal cancer management." (PMID 40003985, 2025).
edema (25 papers, 2009 to 2026). An abnormal accumulation of fluid beneath the skin, or in one or more cavities of the body. "Here we found that treatment with 2-DG (200 mg/kg i.p. prior to the induction of ventilator-induced ALI) was associated with increased pulmonary edema, attenuated gas exchange, enhanced pulmonary neutrophil accumulation as assessed by MPO levels, and cytokine production (IL-6)." (PMID 24086109, 2013). "In an acute model of inflammation (carrageenan-induced paw oedema model) in mice, myeloperoxidase (MPO) activity and NO production were decreased in animals treated with lavender essential oil." (PMID 36902200, 2023). "Then the degree of pulmonary edema, lung pathological changes, myeloperoxidase (MPO) activity, and the production of pro-inflammatory cytokines were detected." (PMID 32038265, 2019). "The evaluation of Evans blue leakage and the determination of MPO activities also indicated that LPS-induced pulmonary edema and leukocytes infiltration were attenuated by 2-DG." (PMID 29552018, 2018). "Moreover, compound 6e showed anti-edema effects in the carrageenan-induced paw edema model in rats and was found to attenuate neutrophil infiltration and myeloperoxidase activity in the inflamed paw tissue." (PMID 41004560, 2025). "Moreover, in the carrageenan-induced paw edema model, it effectively reduced edema, neutrophil infiltration, and myeloperoxidase activity." (PMID 41004560, 2025). "Further an investigation also disclosed that the ethyl acetate extract of S. montagneana decreased LPS-induced iNOS protein expression in RAW 264.7 cells and suppressed pro-inflammatory mediators, such as iNOS, IL-1β, and myeloperoxidase (MPO), in carrageenan-induced rat paw edema." (PMID 38136188, 2023). "In vivo, pulmonary inflammation, pulmonary edema, ultrastructure changes of type II alveolar epithelial cells, MPO activity, total cells, neutrophils, macrophages, TNF-α, IL-6 and IL-1β in BALF, along with the expression of VCAM-1 and VEGF were dose-dependently attenuated by andrographolide." (PMID 23437127, 2013). "Therefore, the MPO activity of carrageen-induced paw edema in mice was measured." (PMID 24223056, 2013). "IL-36 administration exacerbated pulmonary edema, inflammatory cytokine levels (IL-10,TNF-α,MPO) and histopathological injury." (PMID 42103804, 2026). "Methotrexate administration resulted in increased levels of TNF-α, MPO, GATA3, caspase-3, and pulmonary edema indices, while reducing the levels of TAC, SOD, Gpx, IL-10, T-bet, and FOXP3." (PMID 38245672, 2024). "Reduced the cell number, protein concentration, and cytokines/chemokines in the bronchoalveolar lavage fluid (BALF) Reduced myeloperoxidase (MPO) activity, lung injury score, and pulmonary edema Protected against lung injury." (PMID 36579343, 2022). "In dextran-induced paw edema model, LEO at doses of 75 and 100 mg/kg reduced paw edema and MPO activity." (PMID 29743918, 2018). "In carrageenan-induced paw edema model, LEO treatment at doses of 75, 100, and 250 mg/kg reduced edema formation, MPO activity, and NO production." (PMID 29743918, 2018). "Our experimental results showed that MP could inhibit carrageenan-induced abdominal edema and downregulate MPO, TNF-α, and iNOS at the protein level, which is similar to the effect of MP in carrageenan-induced paw edema in rodents." (PMID 25141004, 2014). "This study showed that high tidal volume ventilation increased total protein, IL-1β, IL-6, RANTES, neutrophil counts, and MPO activity in the BALF and induced lung edema, GEF-H1 and active RhoA expression, Rho-kinase activation, and ultrastructural evidence of endothelial destruction." (PMID 25019086, 2014).
lung disease (25 papers, 2010 to 2025). "C5a levels also correlated positively with concentrations of other sputum markers associated with worse CF lung disease including neutrophil elastase (P < 0.001), myeloperoxidase activity (P = 0.006) and DNA concentration (P < 0.001)." (PMID 28278205, 2017). "Indeed, once AAV patients with kidney disease achieve complete remission, they have a much lower relapse risk (usually patients with MPA/anti-MPO+), compared with those with lung disease (usually patients with GPA/anti-PR3+)." (PMID 39107924, 2025). "MPO and its derived oxidant HOCl may induce lung diseases by causing oxidative stress and inflammatory responses." (PMID 38275657, 2024). "CF sputum neutrophil counts, concentrations of myeloperoxidase, NE, and neutrophil chemoattractants correlate with lung disease progression (52, –, 55)." (PMID 39248473, 2024). "Active MPO immunization of the GN-susceptible Wistar Kyoto (WKY) rat strain results in loss of tolerance to MPO with ANCA, mild GN and at times pulmonary disease." (PMID 32373109, 2020). "A variation of these models in rats investigated the role of products released from activated neutrophils, including MPO, in the pathogenicity of MPO-ANCA, especially in the development of ANCA-associated pulmonary disease." (PMID 32373109, 2020). "The effects of eCS on lung disease were measured by HE staining of lung sections, a differential cell counting of bronchoalveolar lavage fluid, a myeloperoxidase (MPO) assay, a real-time qPCR, and Kaplan-Meier survival of mice." (PMID 30630473, 2019). "MPO correlated with inflammatory cells, other inflammatory chemokines, and an oxidative stress marker, and it was thought that MPO was related to lung disorder due to pulmonary inflammation by nanomaterials." (PMID 30352603, 2018). "The association of elevated C5a level with P. aeruginosa recovered from sputum culture and the strong positive correlation of C5a level with neutrophil mediators of CF lung disease, NE, MPO and DNA, provide additional supporting evidence." (PMID 28278205, 2017). "Knowledge gained from this research will help to determine more extensively the biological functions of MPO in inflammatory human lung disease and will aid in the development of potential pharmacological treatments for both acute and chronic lung injury." (PMID 26998194, 2016). "This adds to the suggestion that MPO-ANCA may have a specific role in the pathogenesis of lung disease." (PMID 37331172, 2023). "Furthermore, we analyzed serum levels of myeloperoxidase (MPO), an enzyme produced/secreted by neutrophils and monocytes during oxidative stress in smokers, and involved in both cardiovascular and lung diseases." (PMID 32272606, 2020). "We found that SAHA significantly (p < 0.05) diminishes Pa-LPS induced systemic IL-6 and MPO levels, suggesting its potential as a therapeutic for controlling chronic inflammation and neutrophil-activation mediated obstructive CF-lung disease." (PMID 29301535, 2018). "CF sputum PMN counts, levels of ecDNA, myeloperoxidase (MPO), NE and PMN chemoattractants all correlate with CF lung disease severity." (PMID 34621276, 2021). "The progression of lung disease was monitored by quantifying changes in inflammatory markers (NFκB), cytokines (IL-6/IL-10), neutrophil activity (MPO, myeloperoxidase and/or NIMP-R14) and T-reg numbers." (PMID 29301535, 2018). "This relationship was specific for MMP-9 activity, as neither human neutrophil elastase nor myeloperoxidase activity predicted subsequent lung disease severity in either the RSV or control groups." (PMID 26264019, 2015). "Considering only MPO-ANCA ILD patients that eventually developed kidney disease, median MPO-ANCA titers at lung disease onset were 53 UI/mL (IQR 24.5–259.5), without statistically relevant difference (p = 0.0828) when compared to subjects without subsequent renal disease." (PMID 38445024, 2024).
lung disease (continued). "Second, the lung involvement may be caused by other diseases rather than MPO-AAV because they were not confirmed by the percutaneous pulmonary biopsy, although patients with other lung disease such as tuberculosis and connective tissue disease-associated interstitial pneumonia were excluded." (PMID 37503353, 2023).